Y_RNA (Y RNA )
Gene: Miscellaneous RNA gene on chromosome 3 (38,125,292 to 38,125,394, reverse strand). Ensembl gene ENSG00000201965.
Homologues: Orthologues: chimpanzee Y_RNA (100% identical), macaque Y_RNA (95% identical). Paralogues in human: RNY1 (88% identical), RNY1P11 (87% identical), Y_RNA (86% identical), Y_RNA (85% identical), Y_RNA (84% identical), RNY1P10 (83% identical), Y_RNA (83% identical), RNY1P12 (83% identical), Y_RNA (82% identical), RNY1P13 (81% identical), RNY1P15 (81% identical), RNY1P8 (81% identical), and 95 more.